NRG1 (neuregulin 1)
Diseases named in the same sentence as NRG1 in open-access papers (continued):
Sharing a sentence is not in itself a finding about the gene and the disease.
ischemia (14 papers, 2016 to 2025). A hypoperfusion of the BLOOD through an organ or tissue caused by a PATHOLOGIC CONSTRICTION or obstruction of its BLOOD VESSELS, or an absence of BLOOD CIRCULATION. "Neuroprotection by NRG-1 was also associated with the inhibition of pro-inflammatory gene expression following ischemia." (PMID 27596278, 2016). "NRG-1 is an endogenously produced mediator which is released from the endothelial cells during ischemia." (PMID 39874927, 2025). "Particularly in diabetic cardiomyopathy and after ischemia, Neuregulin-1 is assumed to play a crucial role in myocardial blood supply by inducing coronary collateral formation." (PMID 39940657, 2025). "Using single-cell sequencing, we identified Neuregulin-1-positive macrophages among peripheral blood mononuclear cells that produced Neuregulin-1 post-ischemia." (PMID 40537024, 2025). "The anti-inflammatory properties of NRG1 are bound up with its capacity to suppress proinflammatory gene expression induced by ischemia through NF-κB pathway modification." (PMID 41150741, 2025). "We showed that NRG-1 has a therapeutic window of at least 12 h after 1.5 h of ischemia and reperfusion in a transient MCAO model." (PMID 38638304, 2024). "NRG-1 administration resulted in a significant improvement of neurological function when administered 3 days following ischemia, suggesting a role in neuronal repair." (PMID 38638304, 2024). "Neuregulin‐1 (NRG‐1) is reported to be cardioprotective through the extracellular‐regulated protein kinase (ERK) 1/2 pathway in myocardial ischaemia‐reperfusion injury (MIRI)." (PMID 33470533, 2021). "A transcription factor activity array showed that ETS-1 activity was increased 2-fold, 3 hours following ischemia and this activity was attenuated by NRG1." (PMID 29856744, 2018). "Gene expression profiles of brain tissues following ischemia and NRG-1 treatment were examined by microarray technology." (PMID 27596278, 2016). "To identify transcriptional regulators involved in ischemia-induced inflammatory gene expression, we examined gene expression profiles of brain tissues following ischemia and NRG-1 treatment." (PMID 27596278, 2016). "Furthermore, in vitro and in vivo models of ischemia injury have suggested neuroprotective effects as a consequence of NRG1 intracellular signaling." (PMID 41150741, 2025). "Additionally, human ASC-EVs have recently been shown to prevent muscle damage in a mouse model of critical hindlimb ischemia, mainly through neuregulin 1 protein (NRG1)-mediated signals playing a crucial role in angiogenesis, prevention of inflammation, and muscle protection." (PMID 32316248, 2020). "Since elevated plasma heme and ischemia are signature characteristics of SCA, we hypothesized that NRG-1 would be elevated in children with SCA, and that NRG-1 levels would also correlate with our biomarkers of cerebral injury." (PMID 35935682, 2021). "To examine whether the predicted transcriptional regulators were involved with ischemia and NRG1 neuroprotection, we conducted multiplex transcription factor assays on nuclear extracts from the brains of control, MCAO, and MCAO+NRG1 animals." (PMID 29856744, 2018).
diabetes (13 papers, 2011 to 2025). "In skeletal muscles, diabetes caused a glomerular hemostasis disorder in muscle cells, and on the other hand, NRG1 could cause the glomerular hemostasis in skeletal muscles." (PMID 32509881, 2020). "The results suggested that the exercise training against diabetes-induced hyperglycemia could be associated with an increase in insulin levels, a decrease in blood glucose, and adjustment of NRG1 and ErbB2 proteins." (PMID 32509881, 2020). "Derangements in fatty acid metabolism inherent to DM may be responsible for and linked to diabetes-induced changes in myocardial NRG-1/ErbB signaling." (PMID 23530877, 2013). "Therefore, the role of NRG1 in reducing the oxidative stress associated with diabetes may be a reason for increasing NRG1 in diabetic rats." (PMID 32509881, 2020). "In patients with BC that develop diabetes, neuregulin 1 (NRG1) and epidermal growth factor receptor 3 (ERBB3) overexpression exacerbate tumor growth and progression." (PMID 37389721, 2023). "Aerobic exercise and MOTS-c treatment upregulate NRG1 and ErbB mRNA expression to restore the decreased NRG1/ErbB signalling pathway in diabetes." (PMID 35370955, 2022). "The present research indicated that diabetes increased NRG1 and ErbB2 protein levels and rates of skeletal muscle fibrosis in STZ diabetic rats." (PMID 32509881, 2020). "In summary, results of the present study strongly suggested a mechanism under which the diabetes mellitus increased the fibrosis and NRG1/ErbB2 in skeletal muscles of STZ diabetic rats." (PMID 32509881, 2020). "Diabetes mellitus increased the expression of protein levels of NRG1 and ErbB2 in skeletal muscles of STZ diabetic rats." (PMID 32509881, 2020). "As glucose tolerance was also improved in db/db mice chronically treated with NRG1, our result strengthens the interest of NRG1 as a potential therapeutic agent for diabetes." (PMID 26230680, 2015). "The current study extends this work and is the first to demonstrate that diabetes can alter the expression of NRG1 isoforms in peripheral nerves." (PMID 24252174, 2013). "After 9 weeks and 12 weeks of diabetes, immunoblot analysis with both antibodies showed a significant decrease in the 75 kDa and 65 kDa NRG1 Type III bands in sural nerve." (PMID 24252174, 2013). "None of the subgroups, including age, smoking history, family history of early-onset cardiovascular disease, and prevalence of hypertension, diabetes mellitus or hyperuricemia, profoundly changed the relationship between NRG-1 and MACCEs (all P values for interaction >0.05)." (PMID 40747492, 2025). "Moreover, our findings suggest that MOTS-c activates NRG1-ErbB4 signaling and mimics exercise-induced cardio-protection in diabetes." (PMID 35370955, 2022). "Some studies have reported the potential of NRG1 therapy in diabetes as it may suggest a new pathway in the applied treatment of diabetic myopathy; and strategies such as exercise may reduce or delay muscle fibrosis." (PMID 32509881, 2020). "Since the effect of diabetes on the expression of NRG1 isoforms and erbin in peripheral nerve are unknown, the current study determined whether changes in NRG1 isoforms and erbin may be associated with altered Erb B2 signaling in DPN." (PMID 24252174, 2013). "Data suggests that NRG1 significantly inhibits stress-induced premature senescence in vascular cells in vitro and in the aorta of diabetic mice in vivo, and application of rhNRG-1 for 9 weeks to type 1 diabetic mice attenuates diabetes-induced vascular senescence." (PMID 36120374, 2022). "We initially assumed that diabetes might interrupt the expression level of NRG1 and ErbB2 proteins." (PMID 32509881, 2020). "A recent study showed how treatment with Neuregulin1 (NRG-1) was able to rescue titin-based cardiomyocyte stiffening in diabetic mouse hearts, via increased PKG and ERK1/2 activity and reduced PKCα activity, which reversed the changes in titin-phosphorylation associated with diabetes." (PMID 30425649, 2018).
diabetes (continued). "However, little is known about how diabetes may affect gliotrophic signaling by altering NRG1 levels and Erb B2 signaling in the peripheral nervous system (PNS)." (PMID 24252174, 2013). "In summary, our data support that diabetes may alter Erb B2 signaling in peripheral nerve by altering the balance in NRG1 isoform expression and decreasing the expression of erbin, an adapter protein that can function as a negative regulator of p42/p44 MAPK signaling via Erb B2." (PMID 24252174, 2013). "To elucidate the role of altered NRG1/Erb B2 signaling in DPN, we used diabetic Swiss Webster mice, which after prolonged diabetes develop severe pathophysiologic symptoms of DPN." (PMID 24252174, 2013). "However, diabetes may have tissue specific effects on the expression of NRG1 isoforms." (PMID 24252174, 2013). "The reason why the exercise training decreased NRG1 and ErbB2 levels in soleus and EDL muscles may be due to the fact that it could significantly decrease blood glucose levels in the diabetes mellitus group." (PMID 32509881, 2020). "We hypothesized that NRG-1 could improve cardiac function of diabetic rats, probably by regulating cardiac apoptosis and fibrosis, Streptozotocin (STZ)-induced diabetes (Type I) model is well established for investigating DCM in small animals." (PMID 21798071, 2011). "After success of diabetes induction, the rats with diabetes were treated with (diabetes treated group, n = 8) or without (diabetes group, n = 8) recombinant human Neuregulin-1 (rhNRG-1)." (PMID 21798071, 2011).
diabetic cardiomyopathy (12 papers, 2011 to 2025). Diabetic cardiomyopathy is a disorder of the heart muscle in people with diabetes. "The expression of cardiac NRG1 and the phosphorylation of ErbB2 and ErbB4 are reduced in in vitro (cellular) and in vivo (rat models) of diabetic cardiomyopathy." (PMID 35370955, 2022). "ErbB is a receptor for NRG1, a cardiomyocyte mitogen that increases myocardial angiogenesis in rats with diabetic cardiomyopathy." (PMID 35370955, 2022). "However, in a recent study, administration of recombinant human NRG-1 (rhNRG-1) to STZ-induced diabetic cardiomyopathy rats rescued the depressed cardiac function suggesting that derangements in NRG-1/ErbB may play a causal role in the decreased cardiac function brought about by DM." (PMID 23530877, 2013). "In addition, preclinical studies have supported the therapeutic effects of neuregulin-1 and vericiguat for diabetic cardiomyopathy, which have been effective for treating HF in clinical trials." (PMID 36979641, 2023). "NRG1 treatment improves volume overload, adriamycin-induced LV dysfunction, as well as ischemia and diabetic cardiomyopathy." (PMID 36120374, 2022). "NRG1 attenuates the development of HF in several animal models, including diabetic cardiomyopathy." (PMID 36120374, 2022). "Additionally, previous studies revealed that the neuregulin-1 (NRG1)/ErbB pathway is impaired in diabetic cardiomyopathy cells, which suggested that the NRG1/ErbB pathway may play an important role in diabetic cardiomyopathy." (PMID 30909474, 2019). "However, the effect of NRG-1 on ventricular remodeling in diabetic cardiomyopathy (DCM) remains unclear." (PMID 24223630, 2013). "For example, astragalus polysaccharide exerted protective effects against diabetic cardiomyopathy by activating NRG1/ErbB and AKT/PI3K; exercise increased the level of NRG1 and thus protected cardiac function in rats after infarction." (PMID 35006441, 2021).
pancreatic ductal adenocarcinoma (12 papers, 2021 to 2026). An infiltrating adenocarcinoma that arises from the epithelial cells of the pancreas. "Zenocutuzumab (a HER2/HER3 BSAB) is an orphan drug for NRG1+ pancreatic ductal adenocarcinoma (ORR, 39%)." (PMID 38627681, 2024). "Currently, zenocutuzumab is designated as an orphan drug for pancreatic ductal adenocarcinoma and is on a fast-track approval process for use as standard therapy in advanced NRG1+ cancers." (PMID 38627681, 2024). "The increase of NRG1 will interfere with the effect of chemotherapy on pancreatic ductal adenocarcinoma." (PMID 34692670, 2021). "Activating neuregulin 1 (NRG1) fusions, identified in approximately 0.13–0.5% of pancreatic ductal adenocarcinomas (PDACs), represent a promising therapeutic target." (PMID 41228342, 2025). "Pancreatic ductal adenocarcinoma (PDAC) has been reported to be an NRG1 fusion-enriched tumor; the overall incidence of NRG1 + PDAC is estimated to be 0.48%, and the incidence of NRG1 + PDAC seems to be enriched in KRAS-wild-type PDAC." (PMID 38173003, 2024). "The FDA recently granted accelerated approval in December 2024 for zenocutuzumab, a bispecific antibody targeting HER3-mediated NRG1 signaling, as the first therapy specifically for NRG1 fusion-positive advanced NSCLC and pancreatic ductal adenocarcinoma (PDAC)." (PMID 40576713, 2025). "Indeed, inhibition of HAS2 upon treatment with its specific inhibitor 4-methylumbelliferone (4-MU, also known as hymecromone), has proven successful in reducing tumour stroma in pancreatic ductal adenocarcinoma (PDAC), which also shows high expression of NRG1." (PMID 33692466, 2021). "Importantly, roughly 90% of patients with pancreatic ductal adenocarcinomas have a KRAS mutation but, for those patients without a KRAS mutation, an NRG1 fusion can sometimes be found." (PMID 38369520, 2024).
autism (11 papers, 2007 to 2026). Persistent deficits in social interaction and communication and interaction as well as a markedly restricted repertoire of activity and interest as well as repetitive patterns of behavior. "We genotyped the NRG1 exon 11 missense variant in 146 cases with autism, or autism spectrum disorder, with CVCR ancestry, and both parents when available (N = 267 parents) from 143 independent families." (PMID 17519028, 2007). "NRG1 is expressed in multiple cell-types and best known as a gene affecting a range of psychiatric and neurological disorders such as Alzheimer, autism and schizophrenia." (PMID 37563216, 2023). "This increase significantly correlated with the social interaction subscales of the Autism Diagnostic Interview-Revised (ADI-R), suggesting that NRG1 expression, particularly in microglia, may play a role in the pathophysiology of psychiatric disorders." (PMID 40004071, 2025). "Indeed, NRG1 signaling has been suggested to play a role in the pathogenesis of autism, with evidence indicating an abnormal activation of these pathways." (PMID 40004071, 2025). "In a recent study, Yanan Deng reported that inhibition of the Notch pathway using DAPT alleviated autism-like behaviors and reduced NRG1 and phosphorylated ErbB4 levels, suggesting the involvement of the Notch1/Hes1 pathway in regulating the NRG1/ErbB4 pathway in autism." (PMID 38791584, 2024). "In summary, our data does not support a relationship of the NRG1 exon 11 missense variant with either autism or SCZ in the CVCR, although it does not reduce support for the previous association with SCZ either." (PMID 17519028, 2007). "However, the conflicting and limited information has not yet explained the precise mechanism by which NRG1 contributes to the progression of autism." (PMID 40004071, 2025).
epilepsy (11 papers, 2015 to 2025). A brain disorder characterized by episodes of abnormally increased neuronal discharge resulting in transient episodes of sensory or motor neurological dysfunction, or psychic dysfunction. "Rescue of GABAergic inputs, such as regulating NRG1-ErbB4 signaling, may reduce the risk of epilepsy and intervene in the disease phenotype in APP/PS1 mice." (PMID 38388921, 2024). "We sought to explore whether the administration of exogenous NRG1 could alter epilepsy susceptibility in APP mice." (PMID 38388921, 2024). "Both NRG1 and ErbB4 have been implicated in epilepsy in mouse models and in humans, but a precise role and mechanism for NRG1/ErbB4 in human symptomatic epilepsy, a type of epilepsy with specific etiology and organic brain disease, remain unclear." (PMID 28273943, 2017). "NRG-1/ErbB4 signaling-dependent neuroprotection is vital for host survival in instances of CNS damage such as ischemic stroke, spinal cord injury, epilepsy, and experimental cerebral malaria infection." (PMID 39095837, 2024). "Increased NRG1-ErbB4 protein levels in temporal cortex have been seen in patients with symptomatic epilepsy." (PMID 36224258, 2022). "Interestingly, alteration of Nrg1/ErbB4 signaling is implicated in epilepsy animal models and human patients, and disruption of Nrg1/ErbB4 signaling pharmacologically and/or genetically promotes kindling progression, which results in increased spontaneous seizures in kindling epilepsy model." (PMID 33536056, 2021). "Nevertheless, our study demonstrates an important role of Nrg1/ErbB4 signaling in mediating the anti-seizure effects of KD and provide insight into the epilepsy treatment." (PMID 33536056, 2021). "The results indicated that there are 57 differentially expressed genes in the intervention group and the control group (more than 2 times the expression level), some of which are closely related to epilepsy such as Egr3, Nrg1, Arc, and cox-2." (PMID 31011358, 2019). "Dysfunction of this NRG1/ErbB4 signaling in GABAergic neurons has been reported to induce epilepsy and psychiatric disorders in human where single nucleotide polymorphisms of these proteins were closely linked to E/I imbalance." (PMID 31780806, 2019). "To summarize, we found that the protein levels of NRG1 and ErbB4 were significantly increased, whereas Glu2B and Src phosphorylation were decreased in symptomatic epilepsy." (PMID 28273943, 2017). "Using fresh human symptomatic epilepsy tissues, we found that the protein levels of NRG1 and ErbB4 were significantly increased in the temporal cortex." (PMID 28273943, 2017). "The protein levels of ErbB4 and NRG1 were both drastically increased in the symptomatic epilepsy group." (PMID 28273943, 2017). "Mounting evidence has confirmed the negative regulation of epilepsy by NRG1-ErbB4 signaling." (PMID 38388921, 2024). "Furthermore, we confirmed the inhibitory effect of NRG1 on epilepsy in APP mice via intracerebroventricular infusion." (PMID 38388921, 2024). "Impaired NRG1-ErbB4 signaling exacerbates epilepsy development and seizure spread." (PMID 38388921, 2024). "In addition, this study suggested the important role of NRG1-ErbB4 signaling in the co-morbidity of AD and epilepsy." (PMID 38388921, 2024). "Previous studies have shown that the neuregulin 1 (NRG1)-ErbB4 signaling pathway may regulate the excitability of fast-spiking neurons in the frontal cortex and participate in primary epilepsy pathogenesis." (PMID 28273943, 2017). "However, the exact roles and mechanism for NRG1/ErbB4 in human symptomatic epilepsy are still unclear." (PMID 28273943, 2017). "Here, using symptomatic epilepsy samples from CA patients, we investigated whether NRG1-ErbB4 signaling is altered in human symptomatic epilepsy and the biological consequences." (PMID 28273943, 2017). "We postulated that NRG1-ErbB4 signaling may participate in human symptomatic epilepsy and could be involved in human symptomatic epileptogenesis." (PMID 28273943, 2017).